PMAIP1 (phorbol-12-myristate-13-acetate-induced protein 1)
Diseases named in the same sentence as PMAIP1 in open-access papers (continued):
Sharing a sentence is not in itself a finding about the gene and the disease.
osteoporosis (3 papers, 2024 to 2025). A condition of reduced bone mass, with decreased cortical thickness and a decrease in the number and size of the trabeculae of cancellous bone (but normal chemical composition), resulting in increased fracture incidence. "Additionally, the ROC curve analysis result was meaningful, demonstrating that PMAIP1 can serve as a diagnostic molecular marker for osteoporosis diagnosing." (PMID 38372699, 2024). "This further confirmed that PMAIP1 can delay the progression of osteoporosis and serves as a critical molecule for its treatment and prevention." (PMID 38372699, 2024). "A comprehensive evaluation of all the network analyses, PMAIP1 was defined as osteoporosis’s core gene." (PMID 38372699, 2024). "Comprehensive evaluation of the PPI network, TFs network, drug targets network, ceRNA network analysis results, PMAIP1 were defined as the core genes of osteoporosis." (PMID 38372699, 2024). "In conclusion, the current research was the first to indicate PMAIP1 as a novel biomarker for the diagnosis of osteoporosis." (PMID 38372699, 2024). "In the present study, based on GEO datasets, protein and protein interaction network analysis, transcription factors analysis, drug-gene interaction analysis, and ceRNA network analysis were used to screen the potential hub genes PMAIP1 in osteoporosis." (PMID 38372699, 2024). "After the non-SDEGs added by GeneMANIA to establish the PPI network removed, six up-regulated SDEGs (HIST1H3G, HIST1H2BO, PTP4A1, FAM46A, MT1G and TNFSF9) and one down-regulated SDEG (PMAIP1) were identified as potential hub genes in the pathogenesis of osteoporosis." (PMID 38372699, 2024). "In addition, based on bioinformatic network analysis and relevant experiments, PMAIP1 may be a crucial therapeutic target for osteoporosis." (PMID 38372699, 2024). "Concurrently, si‐PMAIP1 can up‐regulate the expression of p‐AMPK and down‐regulate the expression of p‐mTOR to promote the proliferation and differentiation of osteoblasts and inhibit osteoporosis." (PMID 40681473, 2025).
acute myocardial infarction (2 papers, 2024 to 2025). Necrosis of the myocardium, as a result of interruption of the blood supply to the area. "The increase in PMAIP1 further demonstrates the role of apoptosis in the progression of acute myocardial infarction." (PMID 39650552, 2024). "Phorbol-12-myristate-13-acetate-induced protein 1 (Pmaip1), a BCL-2 protein is essential to apoptosis, regeneration and disease pathways.In an animal model of myocardial infarction/reperfusion, Pmaip1 and BimEL protein levels were elevated after 3 hours of reperfusion." (PMID 41234537, 2025).
adenoid cystic carcinoma (2 papers, 2019 to 2025). A malignant tumor arising from the epithelial cells. "In addition, it has been reported that PMAIP1 has an important role in the induction of apoptosis and autophagy, and was shown to be downregulated in adenoid cystic carcinoma." (PMID 31296259, 2019).
adenoma (2 papers, 2025). A neoplasm arising from the epithelium. "A separate study demonstrated a significant increase in the expression levels of PMAIP1 in invasive gonadotrophic pituitary adenomas compared to non-invasive adenomas." (PMID 40476267, 2025).
Alzheimer disease (2 papers, 2023 to 2024). A progressive, neurodegenerative disease characterized by loss of function and death of nerve cells in several areas of the brain leading to loss of cognitive function such as memory and language. "•PMAIP1 may be a potential biomarker for Alzheimer's Disease." (PMID 38692009, 2024). "MEG3 (ENST00000398461)/hsa-let-7d-5p/ATF6B axis showed importance in Parkinson’s and late Alzheimer’s diseases, while AC092687.3/hsa-let-7e-5p/[SREBF2, FNIP1, PMAIP1] and SDCBP2-AS1 (ENST00000446423)/hsa-miR-101-3p/MAPK6 axes are probably related to Alzheimer’s disease development and pathology." (PMID 38027526, 2023).
esophageal cancer (2 papers, 2017 to 2022). A primary or metastatic malignant neoplasm involving the esophagus.
ischemia (2 papers, 2022 to 2024). A hypoperfusion of the BLOOD through an organ or tissue caused by a PATHOLOGIC CONSTRICTION or obstruction of its BLOOD VESSELS, or an absence of BLOOD CIRCULATION. "ChIP sequencing analyses also showed that FoxO1 binding to the promoter of pro-apoptotic genes, including Bcl2l11, Fadd, Bnip3, and Pmaip1, was decreased in the presence of ischemia or in C/EBP-β-KI, without concomitant increases in C/EBP-β binding to the promoter." (PMID 39060225, 2024).
pituitary adenoma (2 papers, 2023 to 2025). "The expression levels of ANXA2, PMAIP1, SPRY2, C2CD4A, APOD, FGF14 and FKBP10 were significantly upregulated while FNDC5 and MAP3K4 were downregulated in the invasive gonadotrophic pituitary adenomas compared to the non-invasive ones." (PMID 36750863, 2023).
schizophrenia (2 papers, 2015 to 2023). A major psychotic disorder characterized by abnormalities in the perception or expression of reality. "Previous studies have shown that genes such as PMAIP1, DNAJC3, DFFA, and BTG3 are involved in apoptosis, but their specific mechanism of action in schizophrenia needs to be further explored." (PMID 37383091, 2023).
thymoma (2 papers, 2013 to 2015). A neoplasm arising from the epithelial cells of the thymus. "By contrast, the anti-apoptotic make-up of B3 thymomas in the current study was due to the down-regulation of the pro-apoptotic PMAIP1/NOXA gene that plays a role in the mitochondrial apoptosis pathway and drug resistance." (PMID 24427739, 2013).
thyroid cancer (2 papers, 2022 to 2024). "The results showed that eight key genes (NUAK2, TNFRSF10B, TNFRSF10C, TNFRSF12A, UNC5B, and PMAIP1) exhibited good diagnostic performance in differentiating between thyroid cancer patients and controls." (PMID 39104814, 2024). "TNFRSF10B, TNFRSF10C, TNFRSF12A, UNC5B, PMAIP1, and IL18 had increased expression in thyroid cancer tissues, while NUAK2 was decreased." (PMID 39104814, 2024).
bladder cancer (1 paper, 2015). "According to our present study, we demonstrate that BIX-01294 causes apoptosis in bladder cancer cells through ER stress pathway, resulting in PMAIP1 up-regulation and MCL1 down-regulation." (PMID 25685062, 2015). "In summary, our data demonstrate that BIX-01294 induces ER stress pathway, resulting in up-regulation of PMAIP1 and down-regulation of USP9X and MCL1, leading to apoptosis in bladder cancer cells." (PMID 25685062, 2015). "Remarkably, BIX-01294 can enhance the amount of PMAIP1 and reduce MCL1 in bladder cancer cells." (PMID 25685062, 2015).
COVID-19 (1 paper, 2022). A disease caused by infection with severe acute respiratory syndrome coronavirus 2. "Neutrophil transcripts which are robustly expressed in the uninfected state, including anti-proliferation and pro-apoptotic genes (LST1, G0S2, CPPED1, BTG2, PMAIP1) and anti-inflammatory genes (AMPD2, SEC14L1, ZFP36), are significantly downregulated in COVID-19 patients." (PMID 36466858, 2022).
Ewing sarcoma (1 paper, 2016). A small round cell tumor that lacks morphologic, immunohistochemical, and electron microscopic evidence of neuroectodermal differentiation. "TT strongly upregulated the PMAIP1 pro-apoptotic protein in both Ewing sarcoma cell lines, but didn't affect MCL1 expression resulting in less effective apoptosis induction." (PMID 27589063, 2016). "But unlike TT, viscumTT did not upregulate PMAIP1 expression in Ewing sarcoma cells, indicating PMAIP1 regulation is not involved in the synergistic effect produced by viscumTT." (PMID 27589063, 2016).
glioma (1 paper, 2023). A benign or malignant brain and spinal cord tumor that arises from glial cells (astrocytes, oligodendrocytes, ependymal cells). "Activation of the SCARB2/PMAIP1 axis has demonstrated considerable potential in facilitating cell oncolysis and, consequently, eradicating glioma cells." (PMID 37808305, 2023).
liver disease (1 paper, 2021). "PMAIP1 overexpression is linked to NASH and fibrosis histological criteria, which could indicate a worse prognosis of liver disease." (PMID 33785040, 2021).
pulmonary fibrosis (1 paper, 2023). Chronic progressive interstitial lung disorder characterized by the replacement of the lung tissue by connective tissue, leading to progressive dyspnea, respiratory failure, or right heart failure. "PMAIP1 is associated with the radiation-induced pulmonary fibrosis." (PMID 36871016, 2023).
rectal cancer (1 paper, 2023). A primary or metastatic malignant neoplasm that affects the rectum. "For example, the PPP1R13 L rs1970764 variant is a potential prognostic marker for patients with rectal cancer, and the activation of PMAIP1 induces apoptosis in CRC." (PMID 37190215, 2023).
ZIKV infection (1 paper, 2017). "One recent study reported that several apoptotic regulators, including ZMAT3, PMAIP1, TNFRSF10D, BBC3, were upregulated, and cell cycle genes, such as E2F1 and E2F2, were downregulated after ZIKV infection." (PMID 29116029, 2017).
cancer (138 papers, 2008 to 2026). A tumor composed of atypical neoplastic, often pleomorphic cells that invade other tissues. "Although increasing evidence suggests that PMAIP1 is associated with apoptosis, DNA damage, and mitochondrial dysfunction in various cancers, its specific role in TNBC remains unclear." (PMID 41476687, 2025). "PMAIP1 is a gene implicated in various cancers and biological processes." (PMID 39944827, 2025). "Furthermore, interactions between PMAIP1 and mitochondrial dynamics, including changes in mitochondrial membrane potential and mtDNA integrity, are associated with cancer cell apoptosis." (PMID 41476687, 2025). "In conclusion, our research demonstrated that PMAIP1 emerges as a novel pro-cancer factor in FTC, and its knockdown significantly inhibited the proliferation and metastasis of FTC both in vivo and in vitro." (PMID 39944827, 2025). "This is consistent with previous reports and supports the important role of PMAIP1 as a pro‐apoptotic gene in cancer." (PMID 41476687, 2025). "These experimental results suggested that PMAIP1 influences the cancer progression of FTC through the Wnt pathway." (PMID 39944827, 2025). "Studies have shown that PMAIP1 can amplify ROS production and mitochondrial dysfunction in cancer cells, making it a promising target for redox‐based cancer therapy." (PMID 41476687, 2025). "Our discovery found that PMAIP1 played a cancer-promoting role in FTC, representing a significant finding and identifying a potential target for FTC treatment." (PMID 39944827, 2025). "To elucidated the role of PMAIP1 in FTC cancer progression via the Wnt pathway, we conducted a rescue experiment employing shWnt3." (PMID 39944827, 2025). "PMAIP1 emerged as a novel pro-cancer factor in FTC, and its knockdown significantly inhibited the proliferation and metastasis of FTC both in vivo and in vitro." (PMID 39944827, 2025). "In contrast, PMAIP1 expression decreased with advances in the cancer stage, and expression was highest in the LumA subtype." (PMID 37313465, 2023). "PMAIP1 belongs to the BH3-only pro-apoptotic protein of the Bcl-2 family and upregulation of PMAIP1 leads to apoptosis in a variety of cancers." (PMID 31296259, 2019). "Targeting Pmaip1-mediated apoptosis is considered an alternative anti-cancer strategy." (PMID 41008561, 2025). "This raised the question of whether PMAIP1 exerts a pro-cancer effect on FTC by regulating FOSL1 downstream of Wnt." (PMID 39944827, 2025). "Consequently, we posited that our study substantiates, at least in part, the role of PMAIP1 in regulating the cancer progression of FTC via modulation of the Wnt3/FOSL1 pathway." (PMID 39944827, 2025). "To elucidate the pro-cancer role of PMAIP1 in FTC, we conducted further investigations." (PMID 39944827, 2025). "BBC3/PUMA, BMF, BIM, and PMAIP1/NOXA are all more upregulated in cancer cells." (PMID 36195608, 2022). "We found a weak but significant positive correlation between KLF4 and NOXA (gene name PMAIP1) mRNA expression levels (R-score = 0.21 in cancers, R-score = 0.38 in normal tissues) using the total dataset of Gene Expression Profiling Interactive Analysis database." (PMID 33918002, 2021). "However, in vitro studies have shown PMAIP1 plays a crucial role in hepatocarcinogenesis by limiting cancer cell survival and an anti-tumoral function." (PMID 33785040, 2021). "Notably, the PI3K-AKT1-mTOR pathway is involved in the regulation of constitutive PMAIP1 levels in cancer cells, and its inhibition has an impact on the accumulation of PMAIP1 protein." (PMID 30227275, 2018).
cancer (continued). "We analyzed the expression of the four independent prognostic factors (FBXO6, PMAIP1, ERP27, and CHAC1) in BRCA and 32 other cancer types and observed that all four genes were highly expressed in BRCA." (PMID 37313465, 2023). "PMAIP1/NOXA again shows a peculiar behavior, being expressed at higher levels in normal cells and is more consistently upregulated in cancer cells." (PMID 36195608, 2022). "In unstressed cancer cells TRIM28 represses the expression of pro-apoptotic genes: TP53AIP1, BAX, BBC3 (PUMA) and PMAIP1 (NOXA), further suggesting that TRIM28 provides survival advantage to cancer cells." (PMID 28851455, 2017). "Genes that were upregulated by demethylation but not methylated included genes that have been described previously as TSGs in other cancer types (e.g. BAP1, IGSF4, RRM2 (Gautam and Bepler (2006)), PMAIP1, claudin-1; and ICAM1;)." (PMID 18195710, 2008). "PMAIP1, also known as NOXA, is a pro‐apoptotic member of the Bcl‐2 protein family and is involved in the regulation of mitochondria‐mediated apoptosis, DNA damage repair, and oxidative stress responses in various cancers." (PMID 41476687, 2025). "PMAIP1 (NOXA) is a pro‐apoptotic factor that is closely related to cancer development, but its role in triple‐negative breast cancer (TNBC) is unclear." (PMID 41476687, 2025). "Therefore, this is the first research on BAX rs704243, NOXA (PMAIP1) rs78800940 and rs1041978 SNPs in HNC or any cancer." (PMID 39519400, 2024). "Furthermore, the activation of pro-apoptotic genes such as PUMA, phorbol-12-myristate-13-acetate-induced protein 1 (Noxa), Bax, and BH3 interacting domain death agonist (Bid) are of great importance in cancer cells including CRC." (PMID 38190940, 2024). "PMAIP1, a member of pro-apoptotic BH3-only protein family, is located at the outer mitochondrial membrane and plays critical role in the apoptosis induced by many chemotherapeutic agents in cancer cells." (PMID 25685062, 2015). "Consequently, we hypothesized that PMAIP1 is overexpressed in FTC and may exert a pro-cancer effect." (PMID 39944827, 2025). "Although METTL3 is reported to promote translation in human cancer cells independent of its catalytic activity and m6A readers, the METTL3 knockdown resulted in a better association of our candidate mRNAs with polysomes, especially PHLDA1, PIDD1 and PMAIP1, under cisplatin treatment conditions." (PMID 36497162, 2022). "Differential upregulation of BBC3/PUMA, BMF, BIM, and PMAIP1/NOXA between non-transformed and cancer cells was confirmed by RT-PCR." (PMID 36195608, 2022).